VMP1 (vacuole membrane protein 1)
Diseases named in the same sentence as VMP1 in open-access papers (continued):
Sharing a sentence is not in itself a finding about the gene and the disease.
cancer (29 papers, 2012 to 2026). A tumor composed of atypical neoplastic, often pleomorphic cells that invade other tissues. "For instance, the upregulation of VMP1 has been implicated in cancer initiation as well as treatment resistance in pancreatic ductal adenocarcinoma through activation of autophagy." (PMID 41589276, 2026). "MiR-21, miR-210, and miR-124 are three miRNAs that have been associated with the expression of the VMP1 gene, which is itself implicated in cancer pathophysiology." (PMID 39100095, 2024). "In the following paragraphs, we will delve into the relationships between VMP1 and each of these miRNAs, exploring their connections with the mechanisms underlying cancer malignancy." (PMID 38612567, 2024). "VMP1 is a pivotal regulator of cellular homeostasis, with its dysregulation implicated in a myriad of diseases, notably neurodegenerative disorders and cancer." (PMID 39100095, 2024). "In this work, we focus on the post-translational regulation of VMP1 by the ubiquitin system, which is highly implicated in the regulation of metabolic reprogramming in cancer cells." (PMID 37629161, 2023). "High expression of VMP1 has been frequently linked to cancer, and is correlated with increased levels of cell proliferation and autophagy." (PMID 35883670, 2022). "One age-by-sex-associated CpG cg12054453 in TMEM49 (also known as VMP1) was negatively associated with overall cancer survival." (PMID 33919912, 2021). "The autophagy-related protein VMP1 has been linked to the development and progression of cancer." (PMID 34311746, 2021). "Thus far, VMP1's strong involvement in cancer in humans, a disease whose hallmark is cell division gone awry, has been shown to be a result of the protein's roles in cell adhesion and in autophagy." (PMID 24885763, 2014). "Furthermore, VMP1 is essential for the formation of initial cell-cell contacts and tight junction, and its expression level is associated with the invasion and metastatic potential of cancer cells." (PMID 33318473, 2020). "A recent study also described a previously unreported role of VMP1 in regulating the release of proinflammatory molecules in neurodegenerative diseases, in support of a non‐autophagic function of VMP1 in cancer pathogenesis." (PMID 41589276, 2026). "These 17 translocations were further analyzed in 1,059 mutation-negative NSCLCs, which resulted in the identification of two additional tumors with ADK::KAT6B rearrangement and one carcinoma carrying RPS6KB1::VMP1 fusion." (PMID 40661875, 2025). "These efforts led to the identification of two additional tumors with ADK::KAT6B rearrangement and one carcinoma carrying RPS6KB1::VMP1 fusion." (PMID 40661875, 2025). "MiR-21 is frequently upregulated in cancer and is located near the 3′-untranslated region of the VMP1 gene." (PMID 39100095, 2024). "By deciphering the molecular mechanisms linking VMP1 to cancer progression, this exploration paves the way for innovative therapeutic strategies to disrupt these pathways and potentially improve treatment outcomes." (PMID 38612567, 2024). "VMP1 modulation by miRNAs contribute to the multifaceted aspects of cancer biology, influencing processes from cell proliferation to metastasis and patient outcomes." (PMID 39100095, 2024). "The focus is on molecular mechanisms, connections to malignancy, interactions with micro-ribonucleic acids (miRNAs) in a cancer context, and instances of VMP1 gene fusion with other genes in cancer." (PMID 38612567, 2024). "The available data in the bibliography highlight the multifaceted role of VMP1 in various aspects of cancer, encompassing initiation, metastasis, drug resistance, and resistance to cell death." (PMID 38612567, 2024). "In the existing body of literature, VMP1 has been known to fuse with various genes across diverse cancer types." (PMID 38612567, 2024).
cancer (continued). "This review comprehensively examines the relevant literature, elucidating the intricate interplay between autophagy and cancer, as well as the diverse roles of VMP1 in different cancer types." (PMID 38612567, 2024). "Collectively, these findings highlight the intricate involvement of miR-210 and VMP1 in various cancer types, emphasizing their roles in cancer progression, metastasis, and poor prognosis." (PMID 38612567, 2024). "In our study, VMP1 is identified as a novel oncogene and biomarker with a characterized cancer-promoting role in GBM development." (PMID 34311746, 2021). "The expression of VMP1 was significantly decreased in CRC tissues compared with adjacent non-cancer tissues." (PMID 34631221, 2021). "Consistent with the results of the KEGG pathway analysis, GSEA confirmed that cancer-related pathways were enriched in the VMP1 high-expression group, further supporting the potential tumorigenic effect of VMP1." (PMID 34311746, 2021). "As reported, VMP1 protein not only affects the occurrence of autophagy, but also is involved in the proliferation and metastatic potential of cancer cells." (PMID 33318473, 2020). "miR-21 and VMP1 are co-expressed across multiple cancer types (R = 0.52, 0.36, 0.61, 0.39; FDR = 0, 0.003, 0, 4.18e-12, in breast, lung, pancreas, and cervical cancers, respectively)." (PMID 30785618, 2018). "The examination of VMP1’s interactions with micro-ribonucleic acids (miRNAs), including miR-21, miR-210, and miR-124, enhances our understanding of its regulatory network in cancer." (PMID 38612567, 2024). "VMP1 is also reported to be regulated by miR-124a, which impacts muscle cell behavior in goats, suggesting a broader role for miR-124 in cellular processes beyond cancer." (PMID 39100095, 2024). "Notably, VMP1 appears to play a dual role, as its promotion of therapy resistance contrasts with its inhibitory impact on cancer spread, leading to decreased proliferation and invasion." (PMID 38612567, 2024). "Building on these early findings, VMP1’s expression patterns and its functional implications vary significantly across different cancer types, adding another layer of complexity to our understanding of its role in cancer biology." (PMID 39100095, 2024). "Further complicating the role of VMP1 in cancer is its interaction with multiple miRNAs." (PMID 39100095, 2024). "Furthermore, the interplay between VMP1 and microRNAs (miRNAs), which are known to modulate its expression and contribute to cancer progression, will be discussed." (PMID 39100095, 2024). "Mass spectrometry and immunoprecipitation showed that the cell division cycle protein cdt2 (Cdt2), the substrate recognition subunit of the E3 ligase complex associated with cancer, cullin–RING ubiquitin ligase complex 4 (CRL4), is a novel interactor of VMP1 and is involved in VMP1 ubiquitination." (PMID 37629161, 2023). "Furthermore, we show that VMP1 contributes to cancer development and progression via the regulation of autophagy." (PMID 34311746, 2021). "Vacuolar membrane protein 1 (VMP1) is considered to be an important protein in cancer." (PMID 34631221, 2021). "It has been reported that VMP1 expression is enhanced in several cancers." (PMID 34311746, 2021). "In addition, VMP1 is also an essential protein involved in autophagy, cell proliferation, invasion, and metastatic potential of cancer cells." (PMID 33318473, 2020). "In addition, studies have shown that vmp1 is essential for the initial cell–cell contact and tight junction process, and its expression level is related to the invasion and metastasis potential of cancer cells." (PMID 36012210, 2022). "The most frequently observed fusion partner of VMP1 is RPS6KB1, identified in multiple cancer types." (PMID 38612567, 2024). "We found expression of genes involved in cancer proliferation (PARP14, VMP1, APOE) in the mBc4 cluster." (PMID 36153593, 2022).
cancer (continued). "The dysregulation of significant cancer-related genes (FAM83H, CXCL12, PITPNA, HMOX1, DGKZ, NR5A2, VMP1, and ID1) was confirmed by qRT-PCR." (PMID 36232920, 2022). "Autophagy-related genes BID, EIF4EBP1, VMP1, SPHK1, and CX3CL1 also play essential roles in other cancers." (PMID 33224313, 2020). "It has been reported that miR-210 may directly bind to vacuole membrane protein 1 (VMP1) and promote cancer metastasis." (PMID 22703336, 2012). "A limitation of the present study is that primary GBM or patient‐derived xenograft models, which better recapitulate the brain TME, were not included, and whether VMP1‐mediated angiogenesis occurs in other cancer types remains to be explored." (PMID 41589276, 2026).
infection (11 papers, 2018 to 2025). The state of being infected such as from the introduction of a foreign agent such as serum, vaccine, antigenic substance or organism. "This review has highlighted the multifaceted roles of VMP1 in regulating autophagy, maintaining calcium homeostasis, and responding to cellular stress and infection." (PMID 39100095, 2024). "Notably, both TMEM41B and VMP1 are essential for the infection of various viruses, including SARS-CoV-229–31." (PMID 40038246, 2025). "In addition, infection enriched ER scramblases TMEM41B/VMP1 (regulators of autophagy, LD biogenesis and phospholipid equilibration), indicating that they likely interact with these CE-rich LDs." (PMID 41306517, 2025). "Surprisingly, TBK1 was pre-activated in both TMEM41B KO and VMP1 KO cells prior to infection." (PMID 35939522, 2022). "Vmp1, thus, plays a critical role during the early infection stages." (PMID 34093627, 2021). "For rDEN2Δ30 infection, higher baseline expression of myeloid nuclear differentiation antigen (MNDA), and cell surface associated cellular processes such as tetraspanin CD37, integral membrane 2B (ITM2B), and genes involved in autophagy (VMP1) was associated with protection from rash." (PMID 34031380, 2021). "According to this study, they identified the vacuole membrane protein 1 (VMP1), transmembrane protein 41B (TMEM41B), and TMEM64 as host factors required for infection by all these coronaviruses." (PMID 36851792, 2023). "Messenger RNA levels of the autophagy-related genes were significantly elevated at most of the timepoints after infection, except for some genes (Bcl-2, Atg5, Atg12, DRAM1, and VMP1) whose transcription levels declined at 7 dpi." (PMID 33600403, 2021). "Compared to the wild-type (WT) cells, we observed that both TMEM41B KO and VMP1 KO cells were wholly protected from cytolytic infection of flaviviruses and HCoV-OC43, but not alphaviruses." (PMID 35939522, 2022). "Additionally, knockdown of VMP1 and MPP5 conferred protection from infection." (PMID 37803001, 2023).
neurodegenerative disease (4 papers, 2020 to 2026). A disorder of the central nervous system characterized by gradual and progressive loss of neural tissue and neurologic function. "VMP1’s role in neurodegenerative diseases is equally significant, with its potential as a diagnostic or therapeutic target in conditions like PD." (PMID 39100095, 2024). "Collectively, these studies reveal VMP1 as a negative regulator of inflammatory responses, and we postulate that decreased expression of VMP1 can aggravate the inflammatory sequelae associated with neurodegenerative diseases like PD." (PMID 36747822, 2023).
metabolic disease (1 paper, 2024). A congenital disorder (due to inherited enzyme abnormality) or acquired (due to failure of a metabolically important organ) disorder resulting from an abnormal metabolic process. "Other hub RMITRGs, such as HES1, TMBIM6, TSPAN13, and VMP1, also showed significant associations with metabolic diseases, highlighting the diverse molecular pathways involved in T2D." (PMID 39926598, 2024).
VMP1 also shares sentences with these, for which no sentence is quoted: Crohn disease (4 papers); melanoma (4); cognitive decline (2); Hepatitis (2); lung adenocarcinoma (2); neuroblastoma (2); anal carcinoma (1); anaplastic astrocytoma (1); angiosarcoma (1); blood cancers (1); breast invasive carcinoma (1); coronary heart disease (1); diabetic nephropathy (1); diabetic retinopathy (1); dilated cardiomyopathy (1); Fungal Infection (1); hematological malignancies (1); Hypertension (1); Insulin resistance (1); multiple sclerosis (1); nervous system cancer (1); non-alcoholic fatty liver disease (1); Obesity (1); osteosarcoma (1); ovarian tumors (1); Parkinson (1); prediabetes (1); renal cell carcinoma (1); Sepsis (1); Stroke (1).
A further 5 diseases each share a sentence with VMP1 in 1 paper.